CD4 (CD4 molecule)
Diseases named in the same sentence as CD4 in open-access papers (continued):
Sharing a sentence is not in itself a finding about the gene and the disease.
tumor (continued). "Elevated levels of CD8+, CD8+ /CD4+, and FOXP3+ (major transcription factors of the regulatory T cell lineage) in preoperative tumor-infiltrating T lymphocytes were found to be associated with negative lymph nodes, early disease, and radical hysterectomy." (PMID 37729271, 2023). "In parallel, cancer cells and the TME employ mechanisms to suppress the anti-tumor function of the immune system, often through the recruitment of regulatory CD4+ T-cells (Tregs)." (PMID 38077386, 2023). "One in vitro study has shown that the presence of TGF-β in the tumor microenvironment can reduce OXPHOS in effector CD4+ T cells." (PMID 37746258, 2023). "Evidences also suggest that tumor-derived TGFβ is one of the major drivers for induction of CD4+CD25+FOXP3+ Treg cells from CD4+CD25− T cells." (PMID 38038865, 2023). "Based on GSEA and CIBERSORT analysis, tumor cells with low GPX4 tend to be infiltrated by higher proportion of CD4+ T cell, expression of NOX1 was negatively correlated with M1 macrophage infiltration and ACSL4 was positively close to CD8+ T cell infiltration." (PMID 35855531, 2023). "Local administration of an IL-2-expressing vaccinia virus (VV-IL-2) significantly reduced tumor burden, due to the increase in the activity of immune cells including CD4+ and CD8+ T cells and α,β T-cell receptor diversity in a malignant pleural disease model." (PMID 37345057, 2023). "By contrast, NEC-induced tumor suppression and CD4+ T cell infiltration was comparable between WT and Ifngr−/− mice." (PMID 38196632, 2023). "further showed that targeting tumor antigens to B cells via CD19 induced strong antibody responses, and both CD8+ and CD4+ cell responses, which were able to suppress tumor growth." (PMID 37662903, 2023). "Regardless, CD1a-expressing DCs, cells typically responsible for polarizing naïve CD4+ T cells into an anti-tumor Th1 phenotype, were scarce in BCC peritumoral infiltrates." (PMID 37173918, 2023). "Infiltration of T cell CD4 + activated is helpful for maintaining the viability of NK cells, which exert tumor inhibition functions." (PMID 37237274, 2023). "The correlation factor between invasion front and tumor center for CD4+ lymphocytes, CD8+ lymphocytes, CD68+ macrophages, CD163+ M2-macrophages and M1-macrophages were 0.3841, 0.6587, 0.5831, and −0.0658 respectively." (PMID 36836239, 2023). "A higher regulatory T cells to CD4 cells ratio was found in tumor tissue in upfront surgery and FOLFIRINOX patients." (PMID 37587309, 2023). "Thirty years of research have shown that CD4+ T cells are significant participants in human tumor rejection." (PMID 38328405, 2023). "The Authors reported the antitumor effect of Ldha knockdown inhibiting glycolytic reprogramming and restoring CD4 + lymphocytes in the tumor microenvironment." (PMID 37301960, 2023). "So far, only few lncRNAs have been studied to determine their functional importance in tumor-infiltrating CD4+ T cell subsets." (PMID 37346034, 2023). "CD4 + memory T cells can release some anti-tumor molecules such as IFN-γ, TNF-α, and Granzyme B. Therefore, a high frequency of these cells in the TME is associated with better survival of patients with cancer." (PMID 37221555, 2023). "The authors showed that PD-L1+ FOXP3+ CD4+ (T-regulatory) cells coexisted with CD68+ and PD- L1+ CD68+ tumour-associated macrophages (TAMs) in the stroma of ARID1Amut low-risk patients." (PMID 37569458, 2023). "Immunization of C57BL/6-tumor-bearing mice significantly reduced tumor growth and resulted in higher infiltration of CD4, CD8 T, and NK mTROP2 specific cells compared to the control groups." (PMID 37629147, 2023). "In the tumor tissue, most communication strengths were downregulated in the Sephin1 group, except the communications of macrophages-macrophages and macrophages-Cd4+ T cells." (PMID 36718369, 2023).
tumor (continued). "Recent studies have demonstrated that HLA class II-restricted TCRs with high reactivity (avidity) to TAAs are also promising tools for the therapy because TAAs-reactive CD4+ T cells play essential roles in tumor eradication." (PMID 36939853, 2023). "As reported, CD4+ T cells are the primary subsets of T cells and can exert indirect inhibitory effects on tumor cells, while the CD8+ T cells are the main effector cells." (PMID 37764221, 2023). "The correlations of ADAR with infiltrating immune cells (tumor purity) including B cells, CD4+ T cells, CD8+ T cells, neutrophils, macrophages, and dendritic cells in the gastrointestinal tumors were analyzed by TIMER." (PMID 36660243, 2023). "T lymphocytes, including CD8+ and CD4+ T cells, play a role in inducing tumor cell apoptosis through the secretion of cytotoxins and cytokines." (PMID 38050283, 2023). "Nonetheless, CD4+ regulatory T cells (Tregs) suppress anti-tumor immunity and promote tumor progression." (PMID 37274252, 2023). "In conclusion, our study indicates that expanded CD4+ CTLs eliminate tumor cells by exerting their cytotoxicity, while possibly attenuating T and B cell activity or acquiring an exhausted or dysfunctional phenotype by expressing IRs and inhibitory molecules." (PMID 38077321, 2023). "There is increasing evidence that alongside the exhausted CD8 T cell compartment in tumours, both memory CD8 and CD4 T cells contribute to the enhanced anti-tumour response induced by ICB." (PMID 37008996, 2023). "Essentially, during disease progression, a reduction in the number of cytotoxic CD8+ T cells and an increase in the atypical CD4+ T cell infiltrate takes place accompanied by a shift from an anti-tumor Th1 to a tumor-promoting Th2-type immune response." (PMID 37190290, 2023). "In the validation cohort, we found TLS frequently located outside the tumor nest, and contain higher densities of B cells and CD4+ T cells than intra and peritumoral IH." (PMID 36853169, 2023). "Vaccination with tumor-derived cDC2s induced the Th17 polarization of CD4 T-cells, reprogramming of pro-tumor macrophages, and a decrease of myeloid-derived suppressor cells (MDSC)—resulting in tumor size reduction in a tumor mice model." (PMID 37190135, 2023). "Compared to chemotherapy alone, neoadjuvant camrelizumab combined with chemotherapy influenced the densities of CD3+, CD4+ and CD8+ T cells, M1 tumor-associated macrophages, CD20+ B cells and T cells expressing PD1 in the tumor microenvironment." (PMID 36969032, 2023). "Depletion of YTHDF1 amplifies DC-mediated anti-tumor immune response including CD4+ and CD8+ T cells infiltration with increased IFN-γ secretion." (PMID 37015927, 2023). "For virally transduced CAR-T cells, CD4+ CAR-T cells are described to be initially slower in tumor killing than CD8+ CAR-T cells, but are therefore less prone to exhaustion and therefore more persistent in the body after antigen exposure." (PMID 37875523, 2023). "As compared to mice receiving only anti-PD1 treatment, we observed that Trp2Vax and TA99-WT or TA99-HL2-KOA1 treatment appeared to increase frequencies of tumor-infiltrating macrophages, CD4+ and CD8+ T cells, while decreasing the frequencies of monocytes." (PMID 36911698, 2023). "In a lung cancer model with high expression of the chemokine ligand 9 (CXCL9), CXCL11, and granzyme B, cryptotanshinone was shown to increase the infiltration of CD8+ T and CD4+ T cells in the TME to enhance the anti-tumor effect of PD-1 blockade therapy." (PMID 37631380, 2023). "In established tumours, CD4+ TH1 TILs displayed high PD-1 expression, which was also associated with polyfunctional IFN-γ and TNF production ex vivo." (PMID 37153625, 2023). "Together, these data indicate that ICAM‐1 in cancer cells contributes to the anti‐tumor efficacy of anti‐PD‐1 by activating CD4+ T, CD8+ T, and NK cells." (PMID 37097643, 2023).
tumor (continued). "Unlike synthetic materials that rely on neutrophils to activate antitumor immunity, biological materials require macrophage and CD4+ T cells to inhibit tumor growth." (PMID 37553342, 2023). "The antitumor activity of β-glucan mainly depends on the inhibition of tumor cell proliferation by inducing apoptosis and activating the response of adaptive immune cells such as B-cells, CD-4 cells, and CD-8 cells." (PMID 37081407, 2023). "CD73 expression in tumor was associated with low CD8+ and CD4+ T cells, low immune repertoire diversity, and advanced cancer stage." (PMID 37392167, 2023). "One recent investigation reports increased PD-1 expression and decreased PD-L2 expression on tumor cells compared to healthy CD4+ cells." (PMID 37874473, 2023). "Among the TIICs, memory T cells (MTCs), which constitute a distinct subgroup of CD4+ T helper (Th) cells, have garnered substantial attention owing to their potential contribution to effective anti-tumor immunity." (PMID 37781029, 2023). "Most notably, CD4 + T cell quantities, which are crucial for anti-tumor immunity, were estimated as significantly higher in stage III tumors." (PMID 35881197, 2023). "Second, we analyzed the infiltration of CD8+ and CD4+ T cells and cancer-associated fibroblasts in tumors and explored the correlation between KCTD12 expression and tumor cell stemness, genomic heterogeneity, and diagnostic specificity." (PMID 37626178, 2023). "Collectively, these results suggest that IFNγ produced by tumor-infiltrating T cells induced HLA-II expression on HT-29 cells required for tumor recognition by CD4 CTLs." (PMID 37185301, 2023). "Confocal microscopy showed only very few adoptively transferred eGFP+ TRP-1 CD4+ T cells in local clusters at the invasive margin of established amelanotic tagBFP-labelled HCmel12 CRISPR-ctrl tumours." (PMID 37316667, 2023). "In evaluation of the TME, we found that ITI-3000 induced tumor infiltration of CD4 and CD8 T cells, measured both by flow cytometry and by mIHC." (PMID 37711623, 2023). "Tregs are identified as those suppressing anti-tumor activity by inhibiting, among others, the differentiation of naïve CD4+ T cells into Th1, thus enhancing the tumor development and metastasis." (PMID 36835413, 2023). "CD4+Th1 cells mediated a tumor protective effect in a mouse PDA model and were strongly associated with prolonged survival of human PDA patients." (PMID 37081882, 2023). "T lymphocytes play a central role in the immune system, as CD8+ and CD4+ T‐cells can directly damage tumor cells or generate cytokines that activate effector cells, thereby improving the prognosis of EC patients." (PMID 37519061, 2023). "Next, we investigated how a comparatively small subpopulation of CD4+ effector T cells can eradicate large established tumours." (PMID 37316667, 2023). "PDAC shows increased T regulatory cells infiltration which can suppress anti-tumor effectors including CD4+T cells and CD8+T cells." (PMID 38082307, 2023). "Herein, it is reported that the block of Tim-3 enhances the anti-tumor immunity of STING agonist ADU-S100 by unleashing CD4+ T through targeting Tim3+cDC2." (PMID 37771774, 2023). "ACM derived from OGJ patients with early-stage tumours significantly increased the frequency of naïve CD4+ T cells compared with untreated cells (untrx: 34.53 ± 2.9 vs. early-stage: 43.39 ± 3.1%, p = 0.03)." (PMID 36790524, 2023). "In this study, we also report high levels of CD39 among tumor infiltrating CD4+ T cells via flow cytometry." (PMID 37648263, 2023). "A recent study showed a direct effect of this CAF subtype on CD4+ T cells, which was important to control tumour growth." (PMID 36480035, 2023). "Overall, high levels of CCL1 and CCL18 in OC tissues can recruit CD4+CCR8+ Tregs into tumor tissues by recognizing CCR8 on cells and remodeling their inhibitory phenotypes, making them have stronger immunosuppressive phenotypes and proliferative abilities." (PMID 37950246, 2023).
tumor (continued). "We thus conducted systemic immune checkpoint analysis with both tumour-infiltrating immune cells (CD4 T, CD8 T, Treg, and natural killer (NK) cells) and complementary antigen-presenting cells (APCs) (macrophages, DCs, and tumour cells)." (PMID 37383234, 2023). "ACT with TSCM-like CD4+ T cells results in lower PD-1 expression by CD8+ T cells in the tumor microenvironment and an increased frequency of PD-1+CD8+ T cells in tdLNs." (PMID 37400675, 2023). "Among them, T cell populations such as CD8 and CD4 play a key role in tumor control through mechanisms such as production of proinflammatory cytokines and promotion of plasma cell production." (PMID 37234162, 2023). "Although the birds with depleted combined CD4+/CD8+ T cells were also free of clinical signs of MD or tumor development, they were severely emaciated and exhibited difficulties in breathing." (PMID 36992357, 2023). "It was demonstrated that when CD4+ T cells with tumor-specific TCRs were administered to tumor-bearing mice, it mediated direct cytotoxicity against tumor cells." (PMID 37274252, 2023). "A reduction in tumor charge was also observed after patients received neoantigen-reactive CD4+ T cells." (PMID 37649123, 2023). "Even though the levels of CD8+ T cells correlate with better survival of patients with OC, this effect seems to be dependent on the presence of CD4+ tumor-infiltrating T cells (TIL), where CD25+FOXP3+ regulatory T cells mitigate the effect of CD8+ T cells." (PMID 37445860, 2023). "For T cell subsets, similar to CD8+ T cells at the TC, CD4+ T cells exhibited anti-tumor effects and prolonged the OS of patients with PDAC." (PMID 37405518, 2023). "Tumor-specific CD4+ T cells have been shown to promote CXCL9/10 expression through IFN-γ–dependent mechanisms that increase CD8+ T cell recruitment, particularly of low-affinity T cell receptor (TCR) CD8+ T cell clones." (PMID 38063199, 2023). "The levels of CD8+ T and CD4+ T cells were higher in the tumor tissues of the therapeutic groups than those of the empty vector group." (PMID 37138873, 2023). "Regulatory T cells (Treg), as members of CD4+ T cells, have garnered extensive attention in the research of tumor progression." (PMID 37753092, 2023). "Multiple subsets of CD4+ T have been shown to inhibit tumor immune response, such as Th1, Th2, and Treg cells." (PMID 36173462, 2023). "TPST-1495 induced significant infiltration of tetramer-positive AH1-specific CD8+ T cells and CD4+ FoxP3− cells into the tumor and moderately increased CD49b+ natural killer (NK)-cell infiltration and the ratio of tumor CD8+ to Treg+ T cells." (PMID 37559947, 2023). "Based on previous studies, MTT treatment has been shown to promote CD4+ T cells and reduce regulatory T cells, leading to anti-tumor effects." (PMID 37334386, 2023). "The percentage of CD4+ Th1 was increased after anti-IL-6 treatment and cryo-thermal therapy compared with that in tumor-bearing control." (PMID 37108179, 2023). "The significant increase in the CD8/CD4 ratio suggested that Bif@PAu-NPs + NIR + GM-CSF can trigger an effective anti-tumor immune response." (PMID 37872620, 2023). "Although CD8+ CTLs play the predominant roles in anti-tumor immunity, it is now well-appreciated that CD4+ T cells are pivotal to support the effective anti-tumor CD8+ T cell responses." (PMID 37332039, 2023). "The inflammatory mediators or cytokines secreted by CD4+T cells can support immune evasion and maintain immune homeostasis that modulate anti-tumor immunity and pro-tumorigenic roles." (PMID 38082307, 2023). "This functional response was mediated through elevated expressions of MHC I and IL-15Rα, resulting in increased tumor infiltrating CD4+ and CD8+ T cells." (PMID 37681880, 2023). "According to CIBERSORT, the tumor tissues of patients in the high immune score group are rich in CD4+ T cells and CD8+ T cells (p < .001)." (PMID 36058633, 2023).
tumor (continued). "Alternatively, Th1 polarised CD4+ T-cells can promote anti-tumour immunity to destroy tumour cells, either directly or indirectly through effector cells such as CD8+ T-cells." (PMID 36980751, 2023). "Conversely, Hh-deficient CD4+ T-cells adopt Th-1 phenotype, which produces interferon-gamma (IFN-γ) and evokes CD8+ T cell activation and tumor suppression." (PMID 37213270, 2023). "Tumor-associated microglia/macrophages and tumor-infiltrating CD4+ and CD8+ lymphocytes also play important roles in tumor progression and overall survival." (PMID 37833934, 2023). "In this study we have analyzed an oligoclonal CD4+ T cell response to a naturally arising tumor NeoAg at the level of TCR usage and functionality." (PMID 37400675, 2023). "In a spontaneous mouse model of PDAC, co-treatment with gemcitabine and ENO-1 DNA vaccine enhanced CD4 anti-tumor activity and impaired tumor progression." (PMID 36768924, 2023). "Subsequently, the tumor cells (H22 cells and S180 cells) used for murine models of malignant ascites were co-cultured with naive CD4+ T cells or Th1 cells for 48 h; and the apoptosis and proliferative activity of tumor cells were evaluated." (PMID 36690649, 2023). "This process promotes the induction of tumor-specific CD4+ T cells and cytotoxic T cells (CTLs) within the human body, culminating in an anti-tumor effect mediated by immune cells." (PMID 37415744, 2023). "Recent research has highlighted that microaggregates composed of CD8+ (CD103+) T cells, CD4+ T cells and mregDCs within tumour cell beds in oropharyngeal squamous cell carcinoma have remarkable similarities with TLSs." (PMID 36808888, 2023). "After tumor resection, the proportion and absolute number of CD4+Tcm decreased significantly compared with the preoperative values." (PMID 36925914, 2023). "Among various T-cell subsets, CD4+ T-cells (in some cases CD8+ lymphocytes) are more prevalent in the tumor microenvironment and peripheral blood." (PMID 37835465, 2023). "To examine the effect of CD8+ T cell depletion on CD4+ T cells, we analyzed the expression levels of T-bet and IFN-γ in tumor-infiltrating CD4+ T cells." (PMID 36703228, 2023). "ACM derived from OGJ patients with late-stage tumours decreased the expression of PD-1 on the surface of CD4+ T cells (untrx: 78.63 ± 1.5 vs. late-stage: 72.32 ± 3.7%, p = 0.06) compared with untreated cells." (PMID 36790524, 2023). "Targeting CD4+Treg has the potential to become an important approach in immunotherapy as tumor cells in TME can evade immune surveillance by recruiting immune-suppressive cells such as CD4+Treg." (PMID 38250084, 2023). "Targeted therapy of Nrf2 induced tumor infiltration via CD8 + and CD4 + T cells and inhibited tumor progression." (PMID 37996827, 2023). "We then repeated the orthotopic syngeneic transplantation experiment with the mT3-2D KPC cell line and again observed smaller tumors (tumor weight and tumor-to–body weight ratio) in Cd4;Tcf7fl/fl mice compared with control hosts." (PMID 36239683, 2023). "In the context of tumor immunity, tumor cell-mediated cellular immunity performs a vital function which can be categorized into various subtypes such as CD4+ T cells, CD8+ T cells, Treg cells, etc.." (PMID 38078879, 2023). "Although B cells are highly sensitive to tumour cell-specific antigens, these antigens require antigen-antibody interactions mediated by CD4+ T cells with the help of MHC-II molecules." (PMID 36890557, 2023). "Using linear regression analysis, we assessed the association of CD20+, CD8+, CD4+, FOXP3+ TIL-subtypes and CD4+/CD8+, FOXP3+/CD8+ ratios with the expression of HIF1α, LDH5, VD (t1, t2 and t3) and VSA (t2 and t3) in the invading tumor front." (PMID 36900270, 2023). "The tumor immune microenvironment consists of a diverse array of cell types, including CD4+ T cells, CD8+ T cells, B cells, TAMs, natural killer cells, CD1c+ myeloid and CD141+ myeloid dendritic cells, neutrophils, basophils, eosinophils, and mast cells." (PMID 37901223, 2023).